VAV1 (vav guanine nucleotide exchange factor 1)
Diseases named in the same sentence as VAV1 in open-access papers (continued):
Sharing a sentence is not in itself a finding about the gene and the disease.
Obesity (3 papers, 2022 to 2025). Accumulation of substantial excess body fat. "Additionally, we observed that miR-122 inhibition had a stronger effect in the sWAT, resulting in upregulation of direct target genes with beneficial effects on obesity—including Vav1, whose knockout displayed increased fat content by decreasing Sirt1 activity; or Ntrk3, which promotes browning." (PMID 36499248, 2022).
Alzheimer disease (2 papers, 2016 to 2021). A progressive, neurodegenerative disease characterized by loss of function and death of nerve cells in several areas of the brain leading to loss of cognitive function such as memory and language. "A recent study reported that miRNA-330 overexpression in Alzheimer’s disease contributed to the reduction of amyloid β, oxidative stress, and mitochondrial dysfunction by targeting VAV1 through the MAPK pathway." (PMID 33732103, 2021).
asthma (2 papers, 2021 to 2022). "As the targets proteomic analysis located, ITGAL, Syk, and Vav1 remain crucial in the immune regulation of airway inflammation in asthma, particularly T cell regulation." (PMID 36329800, 2022). "We suspected that CAG suppressed the upstream targets ITGAL and Syk and the downstream target Vav1 to decrease the excessive infiltration of leukocytes in the formation of asthma." (PMID 36329800, 2022). "We also simulated the potential binding sites between CAG and ITGAL, Syk, and Vav1 to further confirm that these 3 targets remain important in the therapeutic effects of CAG in asthma." (PMID 36329800, 2022). "The expression levels (the staining intensity) of ITGB2, RAC2 and Vav1 were higher in the asthma group than other groups." (PMID 34618857, 2021). "The levels of most proteins (ITGAM, ITGB2, MMP12, NCF1, NCF2, NCF4, RAC2 and Vav1) were higher in the asthma condition (shown in red) than those in the control condition or after SCIT condition." (PMID 34618857, 2021).
Autoimmunity (2 papers, 2020 to 2021). The occurrence of an immune reaction against the organism's own cells or tissues. "Therefore, VAV1 signalling may be involved in the process of autoimmunity and RA development." (PMID 32380774, 2020).
gastric cancer (2 papers, 2021 to 2023). A primary or metastatic malignant neoplasm involving the stomach. "Another mechanism of action of VAV1 involvement emerged from studies in gastric tumors that showed that the ectopic expression of the RHOA mutant G17E in the human gastric cancer cell line MKN74 triggers VAV1 expression at the mRNA and protein levels, promoting cell migration and invasion." (PMID 37174676, 2023).
hepatocellular carcinoma (2 papers, 2021 to 2025). A malignant tumor that arises from hepatocytes. "Specifically, Vav1 synergizes with KRAS mutations to promote pancreatic cancer, while GEF–H1 facilitates hepatocellular carcinoma (HCC) metastasis by modulating RhoA‐dependent cytoskeletal changes." (PMID 41020039, 2025).
lupus (2 papers, 2020 to 2025). "Immunological disorders also arise from GEF mutations that disrupt lymphocyte signaling, including Vav1 mutations in T‐cell lymphomas, DOCK8 deficiency in hyper‐IgE syndrome, and GEF–H1‐driven Th17 polarization in lupus." (PMID 41020039, 2025). "In the third trimester, systemic lupus erythematosus and proteasome were enriched in the acute disease while Fc gamma R-mediated phagocytosis (VAV1, MARCKSL1, WASF2, DNM2, HCK, MAP2K1 genes) and adherens junction (ACTG1, WASF2, SMAD4, CSNK2B, EP300 genes) represented the subclinical category." (PMID 32012176, 2020).
medulloblastoma (2 papers, 2015 to 2020). A malignant, invasive embryonal neoplasm arising from the cerebellum. "Similarly, VAV1 gene is hypomethylated in medulloblastoma, leading to increased expression of Vav1 protein, which was correlated with the proto-oncogene MYCN amplification." (PMID 32322580, 2020). "Finally, a large screen of medulloblastomas identified widespread expression of Vav1 in the majority of specimens analyzed and Vav1 was demonstrated to play a critical role in medulloblastoma tumor maintenance, with Vav1 abrogation markedly reducing medulloblastoma growth." (PMID 26353933, 2015).
primary immunodeficiencies (2 papers, 2022 to 2024). "Besides, Themis and Vav1 also play an important role in thymic development of T cells and their deficiency might lead to primary immunodeficiencies, as shown for Vav1." (PMID 38565808, 2024).
squamous cell carcinoma (2 papers, 2007 to 2014). A carcinoma arising from squamous epithelial cells. "We previously reported Vav1 expression in 26/57 (45%) malignant lung samples, including adenocarcinoma, squamous cell carcinoma and adenocarcinoma with lepidic growth." (PMID 25313137, 2014). "Moreover, VAV1 was discovered when DNA from five esophageal carcinomas were tested for their transforming activity, which is compatible with the fact that FYN is implicated in squamous cell carcinoma." (PMID 17868464, 2007).
T cell neoplasms (2 papers, 2021 to 2022). "In particular, we focus on the dual role of VAV1 in T cell neoplasms, with an emphasis on tumor cell-driven mechanisms that affect VAV1 control of NOTCH1 signaling." (PMID 34571765, 2021). "The contribution of VAV1 mutations in the development of T cell neoplasms in mice comes as no surprise." (PMID 34571765, 2021).
T-cell leukemia (2 papers, 2017 to 2018). A malignant disease of the T-lymphocytes in the bone marrow, thymus, and/or blood. "A study also showed that Vav1 plays a unique role in T-cell leukemia survival by selectively triggering the Rac2-Akt axis and elevating the expression of anti-apoptotic Bcl-2." (PMID 28029655, 2017).
Thrombocytosis (2 papers, 2024 to 2025). Increased numbers of platelets in the peripheral blood. "To further investigate the role of CD24 in thrombocytosis in MPN, we intercrossed Vav1-Cre;JAK2V617F mice with Cd24-/- mice to generate MPN mice on a CD24-deficient background." (PMID 40373279, 2025).
viral infection (2 papers, 2020). "In addition, other aberrantly expressed genes in response to viral infection include Vav1, which is member of interferon type I and III pathway, leading to cAMP Response Element-Binding Protein (CREB) mediated chromatin remodeling, also contributing to gene specific repression." (PMID 32646047, 2020). "The human protein VAV1 is involved in HIV pathogenesis mediated by HIV Nef protein, that in the early phase of the viral infection ensures T cell activation and allows the establishment of a persistent state of infection." (PMID 33643043, 2020).
acute promyelocytic leukemia (1 paper, 2014). An aggressive form of acute myeloid leukemia (AML), characterized by arrest of leukocyte differentiation at the promyelocyte stage, due to a specific chromosomal translocation t(15;17) in myeloid cells. "In cells derived from Acute Promyelocytic Leukemia (APL), Vav1 is part of interconnected networks of functionally related proteins ended to regulate different aspects of gene expression." (PMID 24962430, 2014).
amyloidosis (1 paper, 2020). A disorder characterized by the localized or diffuse accumulation of amyloid protein in various anatomic sites. "Moreover, patients with the VAV1 rs2546133 T allele and VAV1 rs2617822 G allele presented an increased frequency of vasculitis, amyloidosis and Sjogren syndrome." (PMID 32380774, 2020).
autoimmune myasthenia gravis (1 paper, 2018). "To assess the implication of this Vav1 variant on the susceptibility to antibody-mediated diseases, we used the animal model of myasthenia gravis, experimental autoimmune myasthenia gravis (EAMG)." (PMID 30410484, 2018). "Thus, our data suggest that Vav1 influences susceptibility to myasthenia gravis and this was associated with an impact on TCR repertoire of AChR self-reactive T cells." (PMID 30410484, 2018).
Cognitive impairment (1 paper, 2023). Abnormal cognition is characterized by deficits in thinking, reasoning, or remembering. "We then induced cognitive impairment in both Gca‐Vav1‐CKO and control mice by injecting Aβ into the bilateral hippocampus." (PMID 37949676, 2023).
colon carcinoma (1 paper, 2015). "Besides Vav1, Vav2, a more ubiquitously expressed member of the family of adaptors, also interacts with components of the adhesion complex, e.g. through p120-catenin in SW-480 colon cancer cells." (PMID 25426554, 2015).
common variable immunodeficiency (1 paper, 2019). "Reduced Vav1 expression has been detected in common variable immunodeficiency (CVID) patients with defective TCR mediated signaling." (PMID 30894852, 2019).
diabetic nephropathy (1 paper, 2022). "Among these proteins, increased levels of mannose-binding protein C (Mbl2), cystatin C (Cst3), and proto-oncogene vav (Vav1) might increase the risk of diabetic nephropathy." (PMID 36335368, 2022).
endometrial carcinoma (1 paper, 2018). A malignant tumor arising from the epithelium that lines the cavity of the uterine body. "Because all Vav1, Vav2, and Vav3 were detected by RT-PCR in our endometrial carcinoma cell lines (data not shown), functional compensation may have occurred." (PMID 29872505, 2018).
endometrial neoplasm (1 paper, 2018). Tumors or cancer of ENDOMETRIUM, the mucous lining of the UTERUS. "Then, we analyzed Vav1 expression using a tissue microarray containing human endometrial tumor samples." (PMID 29872505, 2018). "Immunohistochemical analysis revealed that Vav1, a member of the GPCR downstream pathway, was expressed in 139 of the 155 endometrial tumors, and the expression levels of Vav1 and P-REX2a showed a positive correlation (r = 0.44, p < 0.001)." (PMID 29872505, 2018). "However, we could not clarify the direct mechanism, and our data could not show direct evidence that Vav1 functionally cooperates with P-REX2a in endometrial neoplasms." (PMID 29872505, 2018).
endometriosis (1 paper, 2021). The growth of functional endometrial tissue in anatomic sites outside the uterine body. "Another study of the rat endometriosis model suggested that osteopontin, Lyn, Vav1, Runx1, and l-selectin play important roles in the pathogenesis of endometriosis based on gene expression profiling." (PMID 34220510, 2021).
Erythema (1 paper, 2021). Redness of the skin, caused by hyperemia of the capillaries in the lower layers of the skin. "Repetitive topical application of IMQ to the ears of WT mice (Vav1–Cre– p32flox/flox mice) induced psoriatic inflammation with marked erythema, scaling, and stiffness." (PMID 34421919, 2021).
experimental autoimmune encephalomyelitis (1 paper, 2024). An autoimmune demyelinating disease of the central nervous system that is produced experimentally in animals by the injection of homogenized brain or spinal cord in Freund's adjuvant. "We show that the combined mutations in Vav1 and Themis induce a strong attenuation of the severity of Experimental Autoimmune Encephalomyelitis (EAE), contrasting with the moderate effect of the single mutation in each of those two proteins." (PMID 38565808, 2024). "Our results show that combined mutations on Vav1 and Themis induces a strong reduction of the severity of Experimental Autoimmune Encephalomyelitis (EAE), a mouse model of MS, contrasting with the moderate effect of each single mutation." (PMID 38565808, 2024).
glioma (1 paper, 2013). A benign or malignant brain and spinal cord tumor that arises from glial cells (astrocytes, oligodendrocytes, ependymal cells). "Vav1 and Vav3 have independently been shown to be overexpressed in patients with high-grade gliomas; Vav1, however, is overexpressed in peritumoral and perivascular, non-neoplastic astrocytes and thus its role may be related to cross-talk between the microenvironment and glioma cells." (PMID 24109588, 2013).
Immunodeficiency (1 paper, 2024). Failure of the immune system to protect the body adequately from infection, due to the absence or insufficiency of some component process or substance. "We showed that the combined effects of Themis and Vav1 mutations lead to a more severe immunodeficiency than the individual gene mutations alone, suggesting that epistatic interactions between these genes might contribute to stronger immunodeficiency phenotype in individuals affected on both genes." (PMID 38565808, 2024).
leukocytosis (1 paper, 2016). "VAV1-Cre induced DKO mice developed a strong hematological phenotype at postnatal day 10, including severe leukocytosis and hepatomegaly, bone marrow cell hypersensitivity to cytokines including GM-CSF, and rapidly-progressive disease and invariable lethality." (PMID 27449297, 2016).
lung disease (1 paper, 2019). "Because Vav1-hSTING-N154S expression is primarily confined to hematopoietic cells, the lack of lung disease in our model suggests that the expression of constitutively active STING in lung parenchymal cells may be necessary for the lung inflammation to develop." (PMID 31221625, 2019).
lymphoblastic lymphoma (1 paper, 2009). A lymphoma composed of immature small to medium-sized precursor lymphoid cells (lymphoblasts). "We have shown in this report that the double Vav1/Rasgrf2 gene deficiency favors the development and progression of lymphoblastic lymphoma–like tumors in mice." (PMID 20011522, 2009). "Cantrell’s group has also shown that the elimination in thymocytes of RhoA function, a GTPase activated by Vav family proteins, leads to a lymphoblastic lymphoma very similar to the disseminated tumors found in Vav1–/– and Vav1–/–;Rasgrf2–/– mice." (PMID 20011522, 2009). "Unexpectedly, our studies revealed that the inactivation of the Vav1 proto–oncogene favors the formation of lymphoblastic lymphoma–like tumors in aging mice." (PMID 20011522, 2009).
myelodysplastic syndrome (1 paper, 2021). A clonal hematopoietic disorder characterized by dysplasia and ineffective hematopoiesis in one or more of the hematopoietic cell lines. "In this study, we show that female Kdm6aflox/flox mice (with allele inactivation initiated by Vav1-Cre in hematopoietic stem and progenitor cells (HSPCs) have a sex-specific phenotype that emerges with aging, with features resembling a myelodysplastic syndrome (MDS)." (PMID 34780480, 2021).
myeloproliferative disease (1 paper, 2016). "We report here that the VAV1-Cre based CBL/CBL-B DKO mice are born at expected Mendelian ratios but succumb to a rapidly-progressive and fatal myeloproliferative disease beginning in the second week of life." (PMID 27449297, 2016). "Here, using VAV1-Cre-induced conditional CBL/CBL-B double knockout (DKO) in mice, we established an animal model that exhibits a neonatal myeloproliferative disease (MPD)." (PMID 27449297, 2016).
myocardial infarction (1 paper, 2021). Gross necrosis of the myocardium, as a result of interruption of the blood supply to the area, as in coronary thrombosis. "Conditional knockout of Prox1 in Vav1+ compartments revealed that myocardial infarction could promote a significant lymphangiogenic response to improve cardiac function through Vav1+HC and VEGF-C." (PMID 34925642, 2021).
nasopharyngeal carcinoma (1 paper, 2022). A carcinoma arising from the nasopharyngeal epithelium. "We examined the expression of BTK, CD72, PTPN6, and VAV1 in NPC cell lines by qRT-PCR, and the expression levels of BTK, CD72, PTPN6, and VAV11 were lower in human nasopharyngeal carcinoma SUNE-1 cells compared with human nasopharyngeal epithelial cells NP69 (P<0.05)." (PMID 35957889, 2022).
Onset (1 paper, 2023). The age group in which disease manifestations appear. "These processes further inhibit NADPH oxidase activity due to the stimulation of the signaling pathway involved in Vav1 and could be a genetic risk factor for both adult- and juvenile-onset SLE." (PMID 37813633, 2023).
osteosarcoma (1 paper, 2021). A usually aggressive malignant bone-forming mesenchymal neoplasm, predominantly affecting adolescents and young adults. "In addition, four macrophage-related prognostic genes (IL10, VAV1, CD14, and CCL2) had been identified, and the macrophage-related risk model had been validated to be reliable for evaluating prognosis in osteosarcoma." (PMID 34335756, 2021). "All of them were protective genes in this study, and the roles of VAV1 in osteosarcoma still have not been reported." (PMID 34335756, 2021).
prostate carcinoma (1 paper, 2008). A carcinoma that arises from epithelial cells of the prostate gland. "Vav1 functions as an oncogene involved in malignant transformation and the Vav family appears to play an essential role in angiogenesis and androgen receptor transcriptional activity in prostate cancer." (PMID 18925966, 2008).
psoriasis (1 paper, 2025). An autoimmune condition characterized by red, well-delineated plaques with silvery scales that are usually on the extensor surfaces and scalp. "Four genes (SELP, CD93, VAV1, and IL2RG) were identified as the most reliable diagnostic indicators for psoriasis." (PMID 40539722, 2025).
Sepsis (1 paper, 2019). Sepsis is defined as life-threatening organ dysfunction caused by a dysregulated host response to infection. "The mouse sepsis models confirmed two pathways that the ssNN missed: the CD28-dependent VAV1 pathway and the oxidative stress induced senescence pathway." (PMID 30629591, 2019).
Spherocytosis (1 paper, 2015). The presence of erythrocytes that are sphere-shaped. "While Vav1-P1cKO RBCs were overhydrated, scanning electron microscopy of WT and Vav1-P1cKO RBCs revealed that Vav1-P1cKO RBCs had relatively normal discoid morphology, unlike more severe overhydration pathologies such as spherocytosis." (PMID 26001274, 2015).
thrombosis (1 paper, 2019).
type 1 diabetes (1 paper, 2012). "However, it has been proposed as the candidate gene in the Idd18.1 region linked with type 1 diabetes in mouse, and the Vav1/Vav2/Vav3 family is necessary for adaptive immune function in mouse." (PMID 22493691, 2012).
type 2 diabetes (1 paper, 2021). "PAK3, CD44, CD5, SOCS3, VAV1, and PIK3CD are negatively correlated with cardiac systolic function, and P2RY1 is positively correlated with LVEF, which may be referred to in studies on type 2 diabetes." (PMID 34925642, 2021).
Wiskott-Aldrich syndrome (1 paper, 2017). Wiskott-Aldrich syndrome (WAS) is a primary immunodeficiency disease characterized by microthrombocytopenia, eczema, infections and an increased risk for autoimmune manifestations and malignancies. "These genes, namely, Complement C1q A Chain (C1QA), Fc Fragment Of IgE Receptor Ig (FCER1G) Vav Guanine Nucleotide Exchange Factor 1 (VAV1) and Wiskott-Aldrich Syndrome (WAS) were all confirmed to be significantly upregulated." (PMID 29232382, 2017).